KRT17 (keratin 17)
Description:
Type I keratin involved in the formation and maintenance of various skin appendages, specifically in determining shape and orientation of hair (By similarity). Required for the correct growth of hair follicles, in particular for the persistence of the anagen (growth) state (By similarity). Modulates the function of TNF in the specific context of hair cycling. Regulates protein synthesis and epithelial cell growth through binding to the adapter protein SFN and by stimulating Akt/mTOR pathway (By similarity). Involved in tissue repair. May be a marker of basal cell differentiation in complex epithelia and therefore indicative of a certain type of epithelial 'stem cells'. Acts as a promoter of epithelial proliferation by acting a regulator of immune response in skin: promotes Th1/Th17-dominated immune environment contributing to the development of basaloid skin tumors (By similarity). May act as an autoantigen in the immunopathogenesis of psoriasis, with certain peptide regions being a major target for autoreactive T-cells and hence causing their proliferation.
Synonyms: CK-17; K17; 39.1; PC2; PCHC1
Tractability: Antibody: its Gene Ontology location is reachable by antibodies, with medium confidence. PROTAC: UniProt records ubiquitination sites on it; ubiquitination databases record sites on it.
Gene: Protein-coding gene on chromosome 17 (41,619,437 to 41,624,842, reverse strand). Ensembl gene ENSG00000128422.
Subcellular location: Cytoplasm
Subcellular location (Human Protein Atlas): Intermediate filaments
Pathways (Reactome):
Developmental Biology: Developmental Lineage of Pancreatic Ductal Cells; Formation of the cornified envelope; Keratinization
Gene Ontology:
Molecular function: protein binding; structural constituent of skin epidermis; structural molecule activity
Biological process: epithelial cell differentiation; hair follicle morphogenesis; intermediate filament organization; morphogenesis of an epithelium; positive regulation of cell growth; positive regulation of hair follicle development; positive regulation of translation
Cellular component: intermediate filament cytoskeleton; cytoplasm; cytoskeleton; cytosol; keratin filament; cell periphery; cornified envelope
Genetic constraint (gnomAD): Loss-of-function variants: 29 observed, 45.41 expected, observed/expected ratio (o/e) 0.64, 90% interval 0.47 to 0.87. The upper end of that interval is the gene's LOEUF score, 0.87, which puts it in group 3 of 6, group 1 being the genes least tolerant of losing a copy. Missense variants: 536 observed, 592.19 expected, observed/expected ratio (o/e) 0.91, 90% interval 0.84 to 0.97. Synonymous variants: 219 observed, 237.88 expected, observed/expected ratio (o/e) 0.92, 90% interval 0.82 to 1.03.
Homologues: Orthologues: chimpanzee KRT17 (99% identical), rat Krt17 (96% identical), mouse Krt17 (95% identical), rabbit KRT17 (93% identical), pig KRT17 (80% identical). Paralogues in human: KRT14 (79% identical), KRT16 (72% identical), KRT15 (63% identical), KRT19 (60% identical), KRT13 (59% identical), KRT10 (59% identical), KRT12 (57% identical), KRT24 (56% identical), KRT36 (53% identical), KRT27 (51% identical), KRT28 (51% identical), KRT9 (50% identical), and 56 more.
Diseases named in the same sentence as KRT17 in open-access papers:
KRT17 is named in the same sentence as 216 diseases in open-access papers, as found by Europe PMC text mining. Sharing a sentence is not in itself a finding about the gene and the disease. The quoted sentences say what the papers report.
psoriasis (81 papers, 2009 to 2026). An autoimmune condition characterized by red, well-delineated plaques with silvery scales that are usually on the extensor surfaces and scalp. "Histopathological changes were assessed using hematoxylin and eosin staining, while molecular alterations were examined by RT-qPCR analysis of psoriasis-associated keratin genes (Krt16, Krt17, and Krt6a) and evaluation of JAK-STAT signaling activity." (PMID 41976231, 2026). "A crosstalk between non-coding RNAs (ncRNAs) associated with psoriasis and “stress keratins” K6, K16, and K17 (encoded by the genes KRT6, KRT16 and KRT17, respectively)." (PMID 41296428, 2025). "In psoriasis, inactivation of TGFβ/SMAD pathway led to the loss of miR-486-3p, resulting in KRT17 (a cytoskeletal protein that play a pathogenic role in psoriasis) overexpression and keratinocyte hyperproliferation." (PMID 35075118, 2022). "It has been shown that STAT3 is involved in the upregulation of keratin 17, a hallmark of psoriasis, in keratinocytes following IL-17A stimulation." (PMID 27711196, 2016). "Keratin 17 (KRT17) is implicated in the psoriasis pathogenesis and its expression is altered in experiments with transgenic mice overexpressing CCHCR1." (PMID 23189171, 2012). "Studies have found that the KRT17 protein peptide in epithelial cells of psoriasis patients is associated with T cell proliferation and chemotaxis, suggesting it may act as an antigen to promote immune response." (PMID 40574847, 2025). "Thus, KRT17 can be involved in a variety of diseases, including wound healing, activation of immune responses as an autoantigen in the development of psoriasis, and hair loss." (PMID 38205163, 2024). "KRT17 is described as a stress-associated keratin in the skin and a marker of psoriasis." (PMID 39358322, 2024). "Hence, keratin 17 is considered to be a hallmark of psoriasis, a skin inflammatory disease with keratinocyte hyperproliferation." (PMID 24962779, 2014). "KRT17 is ectopically expressed in numerous pathological skin conditions associated with robust inflammation, including wounds, various skin tumors, virus-induced warts and psoriasis, suggesting that KRT17 may also play an important role in immune regulation." (PMID 31374826, 2019). "Strategies to directly suppress KRT17 expression using antisense oligonucleotides or siRNA have shown encouraging results in reducing keratinocyte-driven inflammation in preclinical psoriasis models." (PMID 41479908, 2025). "In psoriasis, KRT17 expression is specifically induced through IFN-γ through the STAT1 signaling pathway." (PMID 41479908, 2025). "CD8+ T cells in psoriasis patients cross-recognize streptococcal M proteins and keratin 17 (K17) via molecular mimicry." (PMID 41009795, 2025). "Given its multifaceted immune-regulatory role, KRT17 and other stress keratins emerge as a therapeutic target in chronic inflammatory skin diseases such as psoriasis, atopic dermatitis, cutaneous lupus erythematosus (CLE), and hidradenitis suppurativa (HS)." (PMID 41479908, 2025). "In psoriasis, KRT17 expression is strongly upregulated in suprabasal keratinocytes, correlating closely with epidermal hyperproliferation and inflammation." (PMID 41479908, 2025). "Another key player in both diseases is overexpression of the keratin 17 (KRT17), which triggers immune responses in psoriasis and serves as an oncogene in cancers like oral squamous cell carcinoma, cervical cancer, and breast cancer." (PMID 39766123, 2024). "KRT17 is described to be upregulated in keratinocytes affected by psoriasis, a chronic inflammatory disease mechanistically resembling wound healing." (PMID 39358322, 2024). "Keratin 16 (K16) and keratin 17 (K17) are established markers of excessive keratinocyte hyperproliferation in psoriasis and are known to promote T-cell activation and psoriasis development." (PMID 38007430, 2023).
psoriasis (continued). "Despite the deluge of studies about KRT17 being carried out in skin appendage development, psoriasis, wound healing and oncology, the relevant studies in diabetic wound healing are scarce." (PMID 37929023, 2023). "Cytoskeletal protein keratin 17 (K17) is highly expressed in the psoriatic epidermis and contributes to psoriasis pathogenesis." (PMID 37497003, 2023). "Oscillibacter was positively correlated with keratin 17 and involucrin and negatively correlated with loricrin, indicating that it was contributing to psoriasis development." (PMID 37111171, 2023). "Some important proteins involved in keratinization, such as KRT6 and KRT17, which have been reported to play a role in psoriasis in previous studies using the IMQ-psoriasis mouse model, were not identified in this study." (PMID 36483564, 2022). "In psoriatic epidermis, Trim21 was found overexpressed and induced activation of STAT3 through ubiquitylating and stabilizing KRT17 in keratinocytes, thus promoting the development of psoriasis." (PMID 35075118, 2022). "Free gallic acid on psoriasis-like skin disease in vivo and in vitro models reduced the mRNA expression of keratin 16 and keratin 17, two biological markers of psoriasis." (PMID 36364354, 2022). "Treatment of human keratinocytes with IL17A, TNF-α and IL-22 upregulates KRT17 by the transcription factor STAT3 that is constitutively phosphorylated in psoriasis." (PMID 33801280, 2021). "The psoriasis-associated cytokines IL-17A, IL-22 and IFN-γ induce the expression of the transcription factor Nrf2 and subsequently KRT17, eventually leading to hyperproliferation of keratinocytes." (PMID 33801280, 2021). "As KRT17 plays a key role in promoting keratinocyte hyperproliferation, we assessed if the psoriasis cytokines were also able to increase KRT17 expression in HPK." (PMID 33801280, 2021). "Subsequently, it turned out that psoriasis treatments such as corticosteroids, retinoids and dithranol downregulate KRT17." (PMID 33801280, 2021). "The most promising extracts in our study (CA, HL and HP) also reduced the KRT17 expression in the in vitro psoriasis model." (PMID 33801280, 2021). "For example, activation of STAT3 by IL-22 is involved in the proliferation of keratinocytes, and activation of STAT3 by IL22 and IL-17A is involved in the induction of keratin 17, which is overexpressed in psoriasis." (PMID 34679602, 2021). "In contrast, narrowband UVB irradiation had a suppressive effect on psoriasis by downregulating the expression of keratin 17 through inhibition of STAT3 activation, depending on the irradiation dose." (PMID 34679602, 2021). "As KRT17 upregulation alters cell proliferation, migration and inflammatory features that contribute to the hyperproliferation in psoriasis, we also analyzed KRT17 expression in our ex vivo psoriasis skin model." (PMID 33801280, 2021). "Abnormal expression of KRT17 has been found in various dermatoses, including psoriasis, alopecia, and pachyonychia congenita (PC)." (PMID 33763026, 2021). "Upon contact with these autoreactive T cells in the skin, KRT17 peptides stimulate T cell proliferation and IFNγ production in psoriasis." (PMID 31374826, 2019). "KRT17 has been identified as a target gene that is suppressed by the TGFBR-SMAD2/3 pathway, and the loss of TGFBR1 expression in psoriatic epidermis contributes to elevated KRT17 expression in psoriasis." (PMID 31374826, 2019). "Nrf2, a transcription factor that is overexpressed in keratinocytes in skin cancer, ichthyosis skin diseases and in psoriasis, has been identified as an important factor promoting keratinocyte hyperproliferation through inducing KRT17 and KRT16." (PMID 31374826, 2019). "Studies from Dr. Wang’s group has established an essential role of T cell-derived cytokines, including IFNγ, IL17A and IL22, in maintaining KRT6/16 and KRT17 expression in the chronic lesion of psoriasis." (PMID 31374826, 2019).
psoriasis (continued). "KRT17 peptides share similar epitopes with virulent factors derived from group A Streptococci, a bacterium that often triggers or exacerbates psoriasis." (PMID 31374826, 2019). "In the case of psoriasis, host antigens must be specific to the skin and joints, and keratin 17 (K17) is the most studied candidate to date." (PMID 29666398, 2018). "In this study, we show that full length keratin 17 elicits a strong T cell proliferation response in psoriasis patients and that proliferation intensity correlates with the patient genotype at the HLA-Cw*06:02 locus." (PMID 29666398, 2018). "Keratin 17 not only reflects the differentiation status of epidermal keratinocytes, but also participates in the pathogenesis of psoriasis by interacting with IL-17A and IL-2232." (PMID 30038329, 2018). "The current study supports the conclusion that keratin 16 and keratin 17 expression in keratinocytes were upregulated by Stat3-dependent mechanisms, accelerating the development of psoriasis." (PMID 26893174, 2016). "IFN induced keratin 17 overexpression is part of a crucial autoimmune loop in psoriasis development." (PMID 24962779, 2014). "For instance, among transcripts increased significantly in human psoriasis, we identified 26 transcripts associated with the “epidermis development” (GO:0008544) gene ontology term (e.g., KRT16, KRT17, ELF3)." (PMID 21483750, 2011). "This cytokine–KRT17–immune cell axis plays a critical role in sustaining inflammation in psoriasis." (PMID 41479908, 2025). "These immune-modulatory functions of KRT17 extend beyond psoriasis." (PMID 41479908, 2025). "Furthermore, KRT17 inhibition has been found to alleviate inflammation in IMQ-induced psoriasis-like dermatitis." (PMID 40346694, 2025). "Moreover, keratin 17 (K17) has been shown to be overexpressed under conditions of hyperproliferative keratinocyte in psoriasis and wound closure." (PMID 40807399, 2025). "In addition to psoriasis and PC, keratin 17 is also involved in the development of other skin conditions, such as lichen planus (LP)." (PMID 39194725, 2024). "Prior studies have shown that cytokeratin-6, cytokeratin-16, and cytokeratin-17, within the same family as CK-19, are upregulated in psoriasis, leading to excessive keratinocyte proliferation – supporting the involvement of the keratin system in this condition." (PMID 38813379, 2024). "Interestingly, the a/a sequence (amino acids 102–116 and 188–196) of keratin 17 closely resembles that of the streptococcal M6 protein, a superantigen in psoriasis." (PMID 39194725, 2024). "Subsequently, studies demonstrated that KRT17 is a stress molecule that plays a regulatory function when the skin is exposed to external stimuli, playing an immunomodulatory function in the development of psoriasis." (PMID 37929023, 2023). "Keratin 17 (KRT17) plays an important role in psoriasis and cancer." (PMID 37762693, 2023). "The core pathological feature of psoriasis and cancer is excessive cell proliferation driven by the abnormal immune microenvironment, metabolic reprogramming, epigenetic reprogramming, and other abnormalities (KRT17 overexpression, lncRNAs, and ROS)." (PMID 37762693, 2023). "Real-time PCR results further confirmed that the mRNA levels of psoriasis-related factors keratin-17, integrin β1, and CXCL9, as well as the mRNA levels of inflammation-related factors IL-1β, IL-6, TNF-α and iNOS, were strongly inhibited in skin of Mincleflox/flox/Lyz-cre+/+ mice." (PMID 37117184, 2023). "These protective effects of gallic acid on psoriasis were related to an unexpected downregulation of Nrf2, which targeted keratin 16 and keratin 17, ameliorating the psoriasis area, the severity index scores, and the epidermal hyperplasia induced by the psoriasis-like disease in mice." (PMID 36364354, 2022). "This confirms the importance of KRT17 as a target for psoriasis therapy." (PMID 34641358, 2021).
psoriasis (continued). "The most effective plant extracts, Humulus lupulus (HL), Hypericum perforatum (HP) and Curcuma amada (CA), were then tested for their effect on the JAK/STAT3 pathway and the marker of hyperproliferation in psoriasis, KRT17, that is regulated by the transcription factor NF-κB." (PMID 33801280, 2021). "Similarly, in a SCID-hu xenogeneic transplantation model, siRNA-mediated inhibition of KRT17 was shown to reduce typical histological features of psoriasis such as increased epidermal thickness." (PMID 34641358, 2021). "In general, the majority of these psoriasis therapies have been reported to reduce KRT17 expression in keratinocytes, suggesting that KRT17 may be critical to psoriasis pathogenesis, and therefore a potential target for therapy." (PMID 31374826, 2019). "Together, KRT17 holds great potential as a new target for the treatment of psoriasis in the future." (PMID 31374826, 2019). "Specifically, we evaluated whether hair follicle-derived keratin 17 can elicit an immune response in psoriasis patients and whether their genotype at the HLA-Cw*06:02 locus can predict the strength of the response to this putative autoantigen." (PMID 29666398, 2018). "In psoriasis, Keratin 17 is a major target antigen of autoreactive T cells." (PMID 27713139, 2017). "The isoform 1 with the non-risk allele induces the expression of keratin 17, a hallmark for psoriasis; the silencing of CCHCR1 reduces its expression in HEK293 cells." (PMID 23189171, 2012). "Therefore, it was suggested that KRT17 may be a critical factor in psoriasis pathogenesis and a good target for therapy." (PMID 33801280, 2021). "Additionally, HL, HP and CA inhibited the activation of the transcription factor NF-κB, which can further influence the expression of KRT17 and is traditionally considered as a positive regulator of inflammation responsible for sustaining the inflammatory environment of psoriasis." (PMID 33801280, 2021). "Simultaneous silencing of multiple psoriasis-related genes such as DEFB4, TSLP, and KRT17 also reduces the level of inflammatory markers." (PMID 40724842, 2025). "In particular, TGF-β1 is significantly upregulated in psoriatic KCs and promotes the overexpression of keratin 17 and the proliferation of KCs through the TGF-β/SMAD/miR-486-3p signaling axis, thereby promoting the development of psoriasis." (PMID 40303401, 2025). "In conditions such as psoriasis and lichen planus, stress-induced keratins (KRT6, KRT16, and KRT17) are highly upregulated, contributing to keratinocyte hyperproliferation, migration, and acting as epithelial alarmins that amplify immune signaling." (PMID 41479908, 2025). "Locally silencing Nrf2 reduced IMQ-induced psoriasis-like dermatitis and inhibited KRT6, KRT16, and KRT17 expression." (PMID 35075118, 2022). "The effect of HL, HP and CA on gene expression of the hyperproliferation marker KRT17, the anti-microbial peptide DEFB4A, the early differentiation marker KRT1 and the glucose transporter GLUT1 were analyzed in psoriasis-like HPK." (PMID 33801280, 2021). "Gallic acid (GA), a natural small molecule from Radix Paeoniae Rubra with an anti-psoriatic effect, has been shown to suppress IL17A-mediated KRT16 and KRT17 expression by preventing activation of Nrf2 in vitro and in the IMQ-psoriasis mouse model in vivo." (PMID 31374826, 2019). "TWEAK/Fn14 signaling contributes to the development of psoriasis by upregulating the TNFR2, EGFR, and keratin 17 expressions in keratinocytes and the IL-6 expression in DMECs." (PMID 30038329, 2018). "It was demonstrated that several peptides on keratin 17 can serve as immunodominant T-cell epitopes and stimulate peripheral blood lymphocytes of HLA DRB1*04 and/or *07 positive patients with psoriasis." (PMID 27713139, 2017).